CD4 (CD4 molecule)
Diseases named in the same sentence as CD4 in open-access papers (continued):
Sharing a sentence is not in itself a finding about the gene and the disease.
Hypertension (continued). "We found that hypertension incidence was 7.6 (95% CI:6.5–8.7) per 100 PYs, and higher incidence was significantly associated with specific traditional (high BMI), and HIV-related risk factors (higher recent VL, lower recent CD4+/CD8+ ratio, lack of exposure of TDF or zidovudine)." (PMID 32487185, 2020). "Therefore, we considered worthwhile to investigate different subpopulations of circulating CD4+ lymphocytes in severely obese patients undergoing bariatric surgery (with or without concomitant hypertension), as well as in normotensive lean controls and in hypertensive lean patients." (PMID 29758052, 2018). "In patients with a history of hypertension (HT), there was a higher percentage of CD8+ T cells and a lower percentage of CD4+ T cells in the acute phase of stroke than those without HT." (PMID 40342517, 2025). "While both CD8+ and CD4+ T cells contribute to the hypertensive phenotype, selective depletion of CD8+ T cells in mice confers partial protection against hypertension, while CD4+ T cell depletion does not." (PMID 39145457, 2024). "Severely ill patients with hypertension had greater frequencies of CD4+ CD62L+ T cells compared to non-severely ill patients with hypertension (p=0.04) and non-severe patients without hypertension (p<0.01)." (PMID 36817450, 2023). "The IgG CMV+ elderly participants diagnosed with hypertension manifested higher values of CD4+ when compared to the IgG CMV+ controls, which can suggest that higher values of CD4+ are not independent of CMV infection." (PMID 35053985, 2022). "The disproportions in naïve and memory T cells, as well as in the CD4/CD8 ratio, were analysed in 99 elderly individuals (71.9 ± 5.8 years) diagnosed with hypertension (n = 51) or without hypertension (n = 48), using an eight-parameter flow cytometer." (PMID 35053985, 2022). "Compared with deaths without hypertension, CRP and LDH increased, and CD4+ cells and CD8+ cells decreased significantly in deaths complicated with hypertension." (PMID 33009426, 2020). "In multivariate analysis, age ≥40 years, non-white race, nadir CD4+T lymphocyte count ≤50 cells/mm3, detectable HIV-1 RNA, and a history of hypertension or CVD remained significant." (PMID 27503230, 2016).
parasitemia (295 papers, 2006 to 2026). "As expected, the loss of CD4 lymphocytes resulted in a large increase in parasitemia, consistent with the loss of both arms of the acquired immune system." (PMID 40972121, 2025). "Even individuals with a CD4 count between 200 and 500 cells/mm3 showed an increased risk of parasitic infections compared to those with higher CD4 counts, with an adjusted odds ratio of 4.6 (95% CI 1.80–11.7, p-value = 0.001)." (PMID 38755680, 2024). "LAG3 deficiency can restore the Th1 immune response of CD4+ T cells and effectively defend against parasitic infections at a late stage." (PMID 37172058, 2023). "An increase in the risk of certain parasitic infections has also been found with a reduction in CD4 lymphocyte count in the peripheral blood of the host." (PMID 35628973, 2022). "Inflammatory responses often play an ambiguous role, with IFN-γ production being associated at the same time with the control of blood parasitemia but also with increased parasite and CD4+ T lymphocyte penetration in the brain." (PMID 34153047, 2021). "Although parasitemia of B. microti declined in CD4-deficient mice, these mice maintained parasites for more than a month." (PMID 34414129, 2021). "The expansion of Tregs associated with higher parasitemia coincided with a contraction of activated CD4 T cells." (PMID 32043415, 2020). "Opportunistic parasitic infections are a major cause of morbidity and mortality in immunocompromized patients, particularly those with low CD4+ counts." (PMID 31142275, 2019). "Risk factors associated with a higher prevalence of opportunistic parasitic infection among HIV patients were low CD4+ counts, persistent diarrhea, poor living conditions, and poor nutrition." (PMID 32546916, 2019). "CD4+ count in HIV patients are risk factors for opportunistic parasitic infections with manifestations of diarrhea." (PMID 32546916, 2019). "Cytotoxic CD4+ T cells are induced through immunization and associate with reduced parasitemia or protection after sporozoite rechallenge." (PMID 29555909, 2018). "Opportunistic parasitic infections have increasingly being associated with low CD4+ counts in HIV individuals." (PMID 30344850, 2018). "The reduction in CD4+ T cell count by the virus predisposes PLWHA to these opportunistic parasitic infections." (PMID 30344850, 2018). "This study further confirms previous reports that increased susceptibility of HIV-seropositive individuals to parasitic infections is associated with CD4+ T-cell counts less than 200 cells/mm3." (PMID 30344850, 2018). "Here, in a large cohort of children aged 6 months to 10 years, we found that recurrent and/or high-density Pf parasitemia was associated with an IL10-dominant CD4 T-cell phenotype, particularly in younger children." (PMID 29097996, 2017). "Low CD4 T-cell count is significantly associated with opportunistic parasitic infections as shown by different studies." (PMID 27048153, 2016). "In a previously published model of chronic P. chabaudi infection in the B cell-deficient mouse, CD4+ T cells and other immune mediators resolve acute infection and control chronic parasitemia to < 1% indefinitely." (PMID 27583554, 2016). "Since eosinophils are known to be associated with CD4+Th2 T cell responses during parasite infections, we next assessed the effector phenotype of the T cells in WT and ΔdblGATA infected mice." (PMID 27332553, 2016). "More importantly, HIV patients with CD4 count less than 50 cells/mm3 were more at risk of opportunistic parasitic infections." (PMID 23451283, 2013). "More so, two proteins — histamine-releasing factor (HRF) and the elongation factor 1α (EF-1α) — were reported to be associated with EVs of P. berghei NK-65 and were implicated with immunosuppression of CD4+ T cells during the blood stages of the parasite infection." (PMID 37219610, 2023).
parasitemia (continued). "To examine this first hypothesis, we evaluated the correlation between parasitemia and CD4+ T cell counts to determine whether this decline in parasitemia was associated with TS or immune reconstitution following treatment." (PMID 36506016, 2022). "For research purposes, we sought to determine the impact of treatment on CD4+ T cell levels and whether there were any associations with parasitemia." (PMID 36506016, 2022). "Indeed, effector memory and central memory CD4+ T cells are associated with protective immunity in some parasitic infections." (PMID 29795573, 2018). "In addition to its role in self-tolerance, PD-1 is linked to pathological antigen-specific CD8+ and CD4+ T-cell dysfunction in chronic infections and parasitic diseases." (PMID 29867989, 2018). "Effector memory Th1 CD4 T cells confer partial protection in the self‐resolutive Plasmodium chabaudi chabaudi (Pcc) model, and loss of T‐bet, a master regulator of Th1 differentiation, impairs control of parasitemia in the Plasmodium berghei ANKA (PbA) model." (PMID 28935714, 2017). "Similarly, CD4 T-cell count <200 was found to be associated with opportunistic parasitic infection (OR = 3.2, 95 % CI 1.2–7.8)." (PMID 27048153, 2016). "A recent report shows that while T. congolense-infected wild-type (WT) and CD4−/− (CD4+ T cell-deficient) BALB/c mice have similar parasitemia and survival time, partial depletion of CD4+ T cells in WT mice leads to lower parasitemia and longer survival than infected normal WT mice." (PMID 27242788, 2016). "In an adoptive transfer and infection system, chronically stimulated memory CD4+ T cells were more protective; they slowed parasite growth, reduced peak parasitemia and were associated with less pathology compared with resting memory cells obtained from infected and drug-cured mice." (PMID 21124875, 2010). "The high parasitemia detected in this patient could be caused by the recent worsening of his CD4 cells count, so he is strictly monitored to survey a possible reactivation of VL." (PMID 20003257, 2009). "The relationship between parasitemia and CD4 + T lymphocyte count has already been investigated in T. cruzi/HIV coinfection." (PMID 41172398, 2025). "Overall, our findings highlight the impact of purinergic signaling in driving CD4+ T cell effector and cytotoxic responses and provide insights into potential purinergic-targeting therapies in the setting of an intracellular parasitic infection." (PMID 40590226, 2025). "Confirmed strongyloidiasis was also associated with having other parasitosis as well as an elevated eosinophil count, hemoglobin, IgE, and, in people with HIV, higher CD4 cell counts." (PMID 39330883, 2024). "Studies to date generally support an important role for CD4 T cells in control of parasitemia and/or clearance of parasites and resolution of infection." (PMID 38392861, 2024). "In contrast to CD4−/− mice, only 50% of the MuMT mice still had detectable parasitemia by 36 days post-primary challenge." (PMID 38392861, 2024). "CD4+ PbT-II cells were transferred into wild-type (WT) and TCRδ knockout (KO) mice, and we monitored parasitemia levels and peripheral blood PbT-II cells after infection with P. chabaudi or P. berghei ANKA." (PMID 39211036, 2024). "Several types of immune cells have been reported to produce IFN-γ during intracellular parasite infections; however, NK cells, and CD4+/CD8+ (double positive) T cells are the most predominant sources." (PMID 38318169, 2024). "Upon secondary challenge, CD4−/− mice demonstrated significantly reduced parasitemia (less than 20%) compared to naïve WT mice (43–60% parasitemia), indicating that some level of protection developed in these animals." (PMID 38392861, 2024). "It is known that CD4+ T cells play an important role in clearing the parasite as CD4-/- mice or mice depleted of CD4+ cells develop a persistent parasitemia." (PMID 39452729, 2024).
parasitemia (continued). "Despite these stable CD4 and viral load values, these three patients had positive parasitemia by cPCR and blood culture or xenodiagnosis in all samples collected before treatment with benznidazole." (PMID 38408095, 2024). "While CD4−/− mice did not clear infection, there was still a significant reduction of parasitemia observed during the primary response in naïve animals, indicating that CD4−/− mice were able to partially control the level of parasites over time." (PMID 38392861, 2024). "CD4−/− and MuMT mice exhibited parasitemia levels that peaked at approximately 45% parasitemia on day 8 post-primary challenge with parasites." (PMID 38392861, 2024). "MuMT mice were more effective than CD4−/− mice in their ability to resolve parasitemia but less effective than WT mice." (PMID 38392861, 2024). "CCR5 is a chemokine that has classically been known as a common co-receptor for HIV on CD4+ T cells, but it also plays a role in other bacterial, viral, and parasitic infections." (PMID 37375499, 2023). "We previously showed that IL‐27ra−/− mice that were infected with Pcc displayed reduced parasitemia during chronic phase and enhanced CD4+ T cell responses following rechallenge with heterologous P. berghei ANKA parasites." (PMID 37855243, 2023). "It is known that leishmanicidal mechanisms, such as NO production from macrophages, are activated by IFNγ-producing CD4+ T cells and are further enhanced by TNFα, promoting resistance against parasite infection." (PMID 36851182, 2023). "CD4+ T cells at the site of initial parasite infection in IFN-γ-YFP reporter mice displayed a higher mean fluorescent intensity than CD8+ T cells at the site, indicative of cells actively producing IFN-γ." (PMID 36695605, 2023). "PLWHA with CD4 counts below 200 cells/mL are more prone to GI parasitic infections and to develop disease complications." (PMID 35746750, 2022). "To further investigate the functional relevance of CD4+ T cells producing IFNγ+ in resistance against parasitemia, we correlated the frequencies of IFNγ+TNF−CD4+ T with antibody reactivity data to Plasmodium proteins that distinguish TBS+ and TBS- Africans17." (PMID 35922467, 2022). "In response to parasitic infections, activated CD4+ Th9 cells can generate the anti-inflammatory cytokine IL-10, which is involved in the maintenance and reestablishment of host immunity." (PMID 35693811, 2022). "Whereas frequencies of CTLA‐4+ TREG cells returned to normal levels after resolution of peak parasitemia, they remained significantly higher than uninfected controls among CD4+ T cells when mice were experiencing asymptomatic recrudescence on day 20 p.i." (PMID 35475529, 2022). "After CD4+ T cells were depleted during the acute phase, the parasitemia of P. chabaudi was greatly increased during this phase, and then fluctuated at high levels." (PMID 35250958, 2022). "The hemogram parameters and CD4+ T cell counts of MSM HIV-positive participants with parasitic infection (Mean ± SD)." (PMID 36067140, 2022). "CD4+ T cells, a major subset of T cells, play a vital role in fighting against parasitic infections via regulating host immune response." (PMID 36310865, 2022). "Effector B cells producing type 2 cytokines (B effector 2 [Be2]) have been shown to be important during parasitic infections, and early expression of IL-4 by these B cells promotes differentiation of type 2 CD4 T cells." (PMID 33383090, 2021). "Decreases in the percentage and total number of CD4+ T cells were detected in both the spleen and peritoneum in an intraperitoneal parasite infection model, together with a reduced percentage of IFN-γ-producing CD4+ T cells and a poor survival." (PMID 34737746, 2021). "Treatment of mice with anti-CD4 MAbs and transfer of naïve mice with CD4+-depleted spleen cells showed significantly higher parasitemia after challenge infection." (PMID 34414129, 2021).
parasitemia (continued). "Supporting these results, the transfer of CD4+ T-cell-depleted spleen cells resulted in higher parasitemia than when CD8+ T-cell-depleted spleen cells were injected." (PMID 34414129, 2021). "Consistent with sequestration of iRBCs, CD8+ and CD4+ T cells were equivalently sequestered in the brain according to the levels of parasitemia in the three infection schemes." (PMID 34025654, 2021). "CD4+ T helper (Th) cells play critical roles in both host humoral and cellular immunity against parasitic infection and in the immunopathology of schistosomiasis." (PMID 34565440, 2021). "Stable Tbet+GATA3+ double positive CD4 T-cell populations were observed during parasitic infections and had decreased IFNγ production upon restimulation." (PMID 35186781, 2021). "T-bet+ Gata-3+ CD4+ T cells can occur in parasite infection, and T-bet/RORγt double-positive cells have been seen in murine experimental autoimmune encephalomyelitis models." (PMID 34216540, 2021). "Stable Tbet+GATA3+ double positive CD4 T-cell populations are produced during parasitic infections and have low IFNγ production upon restimulation." (PMID 35186781, 2021). "Rag1-/- mice reconstituted with CD4 T cells showed similar parasitemia titers, but increased levels of ifng, inos and tnf mRNA as compared to non-transferred infected controls." (PMID 34587172, 2021). "The level of parasitemia in PWH with chronic Chagas disease generally shows an inverse correlation with CD4 counts." (PMID 34842854, 2021). "Consistent with this theory, neutralization of Tregs by Foxp3-depletion led to increased quantities of activated CD4 T cells and rapid control of parasitemia." (PMID 32043415, 2020). "Consistent with this prediction, we show that in Batf3−/− mice on a BALB/c background, CD4 T cells contribute to control of parasite infection." (PMID 32669460, 2020). "A comparison of the percentages of PD1+CD4+ T cells vs. parasitemia showed significant correlations in all groups." (PMID 32733457, 2020). "In the case of Py 17XNL1.1 infections, however, all studies including ours, consistently report a more prominent role for CD4+ T cells in the control of blood stage parasitemia." (PMID 33519801, 2020). "The Th9 cells are a new subtype of a subset of CD4+ T cells producing the cytokine IL-9 and play important roles in promoting effective immunity against tumor and parasites infection in mice." (PMID 32243446, 2020). "It has been shown that chronic parasite infection maintains Ly6C+CD4+ effector T cells, and upon challenge with LmWT parasites these are essential for IFN-γ production that mediates protection." (PMID 32651371, 2020). "In particular, humoral immunity orchestrated by CD4 T cell-dependent antibody responses controls parasitemia and thus allows for the resolution of blood-stage disease." (PMID 32043415, 2020). "Our results revealed administering IL-18 to TLR11xCasp1/11-/- mice during parasite infection dramatically augmented the frequency and absolute numbers of CD4+IFN-γ+ T cells both locally in the peritoneum and in the spleen, compared to non-treated controls." (PMID 31194844, 2019). "During P. chabaudi AS infection, the spleen is the major site of accumulation of CD4+ T cells especially CD4+T-bet+IFN-γ+ Th1 cells that are essential to control parasitemia during the first 2 weeks after infection." (PMID 30915078, 2019). "It should be noted that the increases in CD4+CXCR3+ T cells and CD4+IFN-γ+ T cells observed in the spleen of infected WT mice were coincident with high parasitemia levels in infected CXCR3−/− mice." (PMID 30915078, 2019). "Interestingly, it was found that CD4+ T cell deficient mice infected with T. congolense had significantly lower parasitemia and prolonged survival period compared with their WT mice, suggesting that CD4+ T cells might also contribute to disease pathogenesis and death in infected mice." (PMID 31824512, 2019).